TLR3 (toll like receptor 3)
Diseases named in the same sentence as TLR3 in open-access papers (continued):
Sharing a sentence is not in itself a finding about the gene and the disease.
ZIKV infection (58 papers, 2016 to 2025). "The role of TLR3 rs3775291 has also been investigated in the context of Zika virus infection, with available evidence suggesting an association with congenital Zika syndrome." (PMID 41304172, 2025). "Others have shown that TLR3-mediated immune responses induced by ZIKV infection were associated with the depletion of neural progenitor cells in an organoid model." (PMID 38392915, 2024). "The activation of the innate immune receptor Toll-like receptor-3 (TLR3) by ZIKV infection caused cellular dysregulation and apoptosis; this phenotype was reversed when TLR3 was inhibited." (PMID 34332630, 2021). "Expression levels of viral RNA sensors, such as retinoic acid inducible gene-I (RIG-I), melanoma differentiation associated gene (MDA5), and toll-like receptor 3 (TLR3) were significantly up regulated after ZIKV infection." (PMID 32902370, 2020). "Activation of the Toll-like receptor 3 (TLR3) by ZIKA virus infection was presented as the cause of cell dysregulation and apoptosis, further reinforced by the finding that when TLR3 was inhibited the phenotype was attenuated." (PMID 31867324, 2019). "The pharmacological inhibition or genetic disruption of TLR3 in astrocytes caused a decrease in viral titers and in the viral-induced inflammatory response in infected astrocytes, and partially restored the deficits caused by ZIKV infection." (PMID 36831177, 2023). "Although these findings are preliminary, they suggest that activation of the TLR3 pathway might be used to off-set some of the effects associated with ZIKV infection." (PMID 32941515, 2020). "The organoid models also showed upregulation of Toll-like receptor 3 (TLR3) gene upon ZIKV infection, which was associated with perturbed cell fate differentiation and reduced organoid volume, both of which physiologically mimic clinical manifestations of microencephaly." (PMID 29561796, 2018). "For instance, TLR3 has been shown to both enhance and limit ZIKV infection, underscoring its context-dependent role." (PMID 40733731, 2025). "Selective depletion of RIG-I or TLR3 revealed RIG-I as the primary sensor mediating IFN-β induction upon ZIKV infection, consistent with studies conducted with various human cell types." (PMID 41477009, 2025). "ZIKV infection has been shown to activate intracellular TLRs such as TLR3 and TLR7/8 and to promote a strong pro-inflammatory and antiviral response." (PMID 38839691, 2024). "ZIKV infection considerably increased the expression of TLR3 and therefore the production of IFN-α and IFN-β in infected cells." (PMID 36151059, 2023). "The analysis of the transcriptomic profile of human embryonic stem cell-derived organoids infected with a prototype strain of ZIKV showed that the innate immune receptor Toll-like-Receptor 3 (TLR3) was upregulated after ZIKV infection." (PMID 35251006, 2022). "Our data from our poly(I:C) pre-stimulation studies support previous studies that demonstrated the protection of host cells from ZIKV infection following the activation of TLR3, RIG-I and TLR7/8 pathways." (PMID 35053142, 2022). "Specifically, ZIKV infection of human organoids upregulates the expression of innate immune receptor Toll-Like-Receptor 3 (TLR3), and compounds competitively inhibiting TLR3 can improve ZIKV pathologies." (PMID 33530458, 2021). "A pharmacological administration with a TLR3 competitive inhibitor reduced the phenotypic effects of ZIKV infection." (PMID 34195197, 2021). "Accordingly, upregulation of the innate immune receptor Toll-Like-Receptor 3 (TLR3) was shown after ZIKV infection of human organoids at early days in vitro (15 days), and inhibition of TLR3 reduced the phenotypic effects of ZIKV infection." (PMID 34483818, 2021). "High levels of mRNA of TLR3 and type I/II IFNs were also detected in the peripheral blood of patients with acute ZIKV infection (up to 5 days after the onset of signs/symptoms)." (PMID 33657175, 2021).
ZIKV infection (continued). "Pharmacological inhibition of TLR3 signaling decreased these inflammatory responses, highlighting the role of TLR3 in ZIKV infection." (PMID 34696494, 2021). "Based on transcriptomic analysis, ZIKV infection resulted in an up-regulation of Toll-like receptor 3 (TLR3) expression that derailed cell fate and reduced the number of functional neurons, leading to microcephaly." (PMID 35087520, 2021). "Role of miR-148a in congenital ZIKV infection, targeting TLR3 during Duck tembusu virus (DTMUV) and playing their role in tumor invasion and migration are well known." (PMID 33936086, 2021). "Focusing on hNPCs and induced pluripotent stem cell (iPSC)-derived human astrocytes, we studied the roles of RIG-I, MDA5, and TLR3 in sensing ZIKV infection and in inducing inflammatory as well as antiviral cytokines." (PMID 33658344, 2021). "Further, a previous study with a similar approach testing candidate SNPs demonstrated Toll-like receptor 3 (TLR3) rs3775291 and Tumor Necrosis Factor (TNF) rs1799964 associated with abnormal outcomes due to ZIKV infection during pregnancy." (PMID 34899713, 2021). "Primary human astrocytes significantly increased expression of TLR3 and its downstream adaptor molecules, and thus promoted the release of pro-inflammatory cytokines and chemokines following ZIKV infection." (PMID 34696494, 2021). "That platform also showed an upregulation of the innate immune receptor Toll-like receptor 3 (TLR3) after ZIKV infection of human organoids." (PMID 34195197, 2021). "Researchers found that ZIKV infection leads to the activation of the Toll-like receptor 3 (TLR3), contributing to deregulated neurogenesis and decreased functional neurons." (PMID 33135109, 2020). "Stimulation of TLR3 (using poly I:C) or TLR7 (using Imiquimod) prior to ZIKV infection suppressed viral replication in a dose-dependent manner." (PMID 32941515, 2020). "In their study, TLR3 was upregulated after ZIKV infection and blocking TLR3 signaling ameliorated the phenotypic effects of ZIKV infection." (PMID 30952992, 2019). "Since the TLR signaling pathway has been shown to induce the autophagy pathway via adaptor proteins MyD88 or TICAM, we next investigated a potential link between TLR3 and the autophagy pathway in the context of ZIKV infection and pathology." (PMID 30735502, 2019). "Specifically, ZIKV infection increased the expression of Toll-like receptor 3 (TLR3), retinoic acid-inducible gene I (RIG-I) and melanoma-differentiation factor 5 (MDA5) RNA in human fibroblasts." (PMID 30081445, 2018). "The innate immune receptor Toll-like receptor 3 (TLR3) is upregulated after ZIKV infection; inhibition of TLR3 partially rescued the phenotypic effect of ZIKV in human brain organoids." (PMID 29937727, 2018). "ZIKV infection of human cerebral organoids acts (at least in part) via TLR-3 to elicit a direct neural cell depletion, which is partially abrogated by TLR-3 inhibition." (PMID 27560129, 2016). "Tlr3 was included as an additional pattern recognition receptor because it detects double-stranded RNA and has been shown to modulate the inflammatory response to ZIKV infection in astrocytes, as well as interact with the Rig-i pathway." (PMID 37800949, 2023). "Importantly, a vital role of TLR3 in ZIKV infection has not only been shown in experimental animal models, but it has also been supported by clinical findings." (PMID 36831177, 2023). "In contrast, a TLR3 blockade reduced the phenotypic effects of ZIKV infection." (PMID 36831177, 2023). "Thus, ZIKV infection not only impairs neurogenesis, but also induces activation of caspase-3 and toll-like receptor 3 (TLR3), leading to cell death." (PMID 34681654, 2021). "On the other hand, TLR3 inhibition decreased the phenotypic effects of ZIKV infection." (PMID 34299287, 2021). "The role of TLR3 during ZIKV infection remains even more elusive." (PMID 33658344, 2021).
ZIKV infection (continued). "Hence, while our observations support an antagonistic effect of TLR3- onto RLR-induced signaling, the exact molecular mechanism by which TLR3 activation interferes with the IFN response during ZIKV infection in hNPCs remains to be elucidated." (PMID 33658344, 2021). "Furthermore, they observed the upregulation of the innate immune receptor Toll-like-Receptor 3 (TLR3) after ZIKV infection of human organoids and mouse neurospheres." (PMID 34299287, 2021). "Moreover, pharmacological inhibition of TLR3 during ZIKV infection of cerebral organoids attenuates virus-mediated apoptosis and neurosphere shrinkage." (PMID 33658344, 2021). "A link between ZIKV infection and TLR3-mediated host-innate immune responses was also established." (PMID 34681654, 2021). "Upon ZIKV infection of iPSC-derived astrocytes, we observed an almost 4-fold increase of pSTAT1 in cells treated with the TLR3 inhibitor (top blot, lane 4), whereas phosphorylation of STAT3 was decreased to the level of noninfected cells (compare lane 2 with lane 4)." (PMID 33658344, 2021). "Our observation of increased STAT3 phosphorylation upon ZIKV infection in the presence of TLR3 and the downregulation of STAT1 signaling is in agreement with the well-established interplay between these two transcription factors (recently reviewed in reference 69)." (PMID 33658344, 2021). "Our studies reveal that during ZIKV infection, recognition of viral RNA by TLR3 enhances the production of inflammatory cytokines and suppresses the interferon response triggered by RIG-I-like receptors (RLR) in a SOCS3-dependent manner, thus facilitating virus replication." (PMID 33658344, 2021). "To gain preliminary insight into whether stimulation of IFN response prior to ZIKV infection can decrease or block viral replication, we pre-treated fcMSCs from one of the donors for 1 h with TLR3 or TLR7 agonists poly I:C or imiquimod, respectively." (PMID 32941515, 2020). "However, further investigations are warranted to delineate the role of Axl in ZIKV infection of other testis cell types and potential cross talk between Axl and viral RNA-sensing pathways such as TLR3 and RIG-I in human SC." (PMID 31311882, 2019). "Inhibition of TLR3/dsRNA by competitive inhibitor (thiophenecarboxamidopropionate) resulted in reversal of these phenotypic effects, while treatment with TLR3 agonist (poly I:C) mimicked ZIKV infection in terms of brain organoid volume." (PMID 30374352, 2018). "A proposed mechanism for ZIKV induced microcephaly suggested that ZIKV infection leads to TLR3-mediated hyper activation of innate immune response, which in turn cause transcriptional deregulation of the genes related to neurogenesis resulting in impaired neurogenesis." (PMID 30374352, 2018). "Furthermore, TLR3 inhibition decreased the cytopathic effect of ZIKV infection." (PMID 35251006, 2022). "As hNPCs are capable of mounting an efficient innate immune response in general and express inflammatory cytokines upon ZIKV infection, we hypothesized that TLR3 signaling might be involved in suppressing antiviral responses induced via the RIG-I-like receptor (RLR) pathways." (PMID 33658344, 2021). "A study demonstrated that DCs present in the skin express high levels of TLR3 and TLR7 and play an important role in the immune response against ZIKV infection." (PMID 36151059, 2023). "Transcriptome analysis of ZIKV infection in human cerebral organoids identified the upregulation of toll-like receptor 3 (TLR3), an innate immune receptor, and further demonstrated that inhibition of TLR3 can ameliorate the effect of ZIKV infection." (PMID 30704043, 2019). "A recent study demonstrated that TLR3, MDA5, and RIG-I all play a moderate role in limiting ZIKV infection in primary human skin fibroblasts." (PMID 29988497, 2018). "Altogether, ZIKV infection elicits RIG-1/MDA5- and TLR3-mediated innate immune responses leading to releases of type I and type III IFNs to protect cells from viral invasion." (PMID 29724036, 2018).
ZIKV infection (continued). "While TLR3 recognizes viral dsRNA within endosomal vesicles, RIG-I and MDA5 act as cytoplasmic sensors that frequently function in a redundant manner, as reported in ZIKV infection models." (PMID 41477009, 2025). "TLR3 is an endosomal PRR that recognizes single stranded RNA and its activation has been shown to drive innate responses to ZIKV infection, though whether it plays a protective role is less clear." (PMID 38392915, 2024). "Inhibition of TLR3 in Zika virus-infected brain organoids rescued the effect of the virus on CSPC apoptosis and (at least partially) restored the organoid size, while a TLR3 agonist mimicked the features of Zika virus infection in organoids." (PMID 38075281, 2023). "The activation of both TLR3 and RIG-I pathways has been demonstrated to be protective in the infection of host cells with ZIKV, with the former being shown previously to be protective in an alternative astrocyte model of ZIKV infection." (PMID 35053142, 2022). "TLR3 could be activated by ZIKV by sensing the replication intermediate of viral RNA and was upregulated in human organoids and mouse neurospheres after ZIKV infection." (PMID 34790205, 2021). "To corroborate the negative effect of TLR3 on the antiviral response to ZIKV infection also in human iPSC-derived astrocytes, which express TLR3 in an inducible manner like hNPCs (respectively), we made use of the dsRNA/TLR3 complex inhibitor." (PMID 33658344, 2021). "Our data show that ZIKV infection induces the expression of TLR2, TLR3, and adaptor molecule MYD88." (PMID 30781519, 2019). "Compared to the positive control of PH5CH8 cells, TLR3 agonist poly(I:C) failed to robustly induce TLR3 mRNA expression in human NPCs, nor did ZIKV infection." (PMID 30952992, 2019). "Therefore, the production of TLR3- and RIG-1/MDA5-mediated type I IFN production and subsequent activation of the JAK/STAT innate immune pathway confer increased resistance to ZIKV infection." (PMID 29724036, 2018). "Numerous studies have shown that ZIKV interacts with sensory molecules, such as toll-like receptor 3 (TLR3) and retinoic acid inducible gene 1 (RIG-1), as well as the transcription factors interferon regulatory factor 3 (IRF7) and NFκ-B, following ZIKV infection." (PMID 36014974, 2022). "TLR3 competitive inhibitor also failed to block the phenotypic effects of ZIKV infection." (PMID 30952992, 2019). "Therefore, in our system, ZIKV infection-mediated microcephaly phenotype results from IFN-independent ISG overactivation rather than boosting TLR3 signaling." (PMID 30952992, 2019). "However, in our system, TLR3 agonist poly(I:C) and ZIKV infection failed to robustly induce TLR3 mRNA expression." (PMID 30952992, 2019). "In cells stably expressing TLR3, activation of IRF3 was not substantially affected; however, we observed an ∼50% reduction of STAT1 phosphorylation during ZIKV infection." (PMID 33658344, 2021).
asthma (57 papers, 2011 to 2026). "Previous research has implicated TLR3 in modulating specific phenotypes of allergic conditions such as asthma." (PMID 40842957, 2025). "Specifically, research on aspirin-tolerant asthma found that TLR3 polymorphisms, particularly -299698G>T and 293391G>A [Leu412Phe] were associated with various respiratory phenotypes encompassing asthma." (PMID 40672946, 2025). "The contribution of TLR3 genetic variants to asthma pathogenesis remains an area of investigation, with evidence showing some heterogeneity." (PMID 40672946, 2025). "All nucleic acid sensing endosomal TLRs have been implicated in asthma, wherein TLR3 has been associated with induction, and TLR7, TLR8 and TLR9 are associated in disease exacerbation." (PMID 36498932, 2022). "Currently, mechanisms of how TLR-3 or TLR3 SNP (rs100254050) can lead to susceptibility to severe asthma are unclear." (PMID 31824491, 2019). "It is noteworthy that PAR1 and TLR3 are both up-regulated by respiratory viruses associated with asthma exacerbations and that TLR3 stimulation per se induces RIG-like receptor expression in airway epithelium." (PMID 30423826, 2018). "Primary BECs from patients with asthma have a deficiency in TLR3 and MDA5 signalling, which reduces the production of inflammatory mediators after RV infection." (PMID 30345002, 2018). "A genome-wide association study identified TLR3 as genetic risk factor for suicide in individuals with asthma and with a familial risk for asthma." (PMID 26415953, 2016). "TLR3 activation of both the innate and adaptive immune systems in the airway is associated with the amplification of the inflammatory cascade characteristic of asthma." (PMID 39988665, 2025). "We evaluated whether post-bronchiolitis asthma was associated with polymorphisms in the TLR3 rs3775291, TLR4 rs4986790, TLR7 rs179008, TLR8 rs2407992, TLR9 rs187084, and TLR10 rs4129009 genes." (PMID 28592890, 2017). "Similarly, respiratory syncytial virus (RSV), which is a common cause of asthma exacerbations, particularly in childhood, induces a lymphocytic inflammatory response via TLR3." (PMID 25089623, 2014). "In the case of rhinovirus infection, the most common cause of asthma exacerbations at any age, dsRNA elicits TLR-3–mediated antiviral responses in the bronchial epithelium through the activation of TIR-domain-containing adapter-inducing interferon-β (TRIF) pathway." (PMID 25546419, 2014). "However, despite correlations observed between TLR3 genetic variants and various asthma and allergic phenotypes, the specific impact of these variants on asthma susceptibility and severity exhibits considerable heterogeneity across different populations and studies." (PMID 40672946, 2025). "Notably, IRF2 is required for induction of TLR3 and other interferon-inducible genes critical to mount antiviral responses and severe viral respiratory infection in early life is a risk factor for asthma development in later childhood." (PMID 38974097, 2024). "In animal models of asthma, stimulation of the TLR3/TRIF signaling pathway has been demonstrated to exacerbate airway inflammation, promote inflammatory cell infiltration, and worsen the severity of the asthma response." (PMID 40672946, 2025). "This inconsistency underscores the complex and multifactorial nature of TLR3’s regulation within the context of asthma pathogenesis." (PMID 40672946, 2025). "Functionally, TLR3 is known to mediate viral recognition and subsequent inflammatory responses, processes that are believed to significantly influence asthma progression." (PMID 40672946, 2025). "Further studies are required to identify the roles of TGF‐β1, IL‐7R, and TLR‐3 in asthma management." (PMID 39575691, 2024). "In rats intraperitoneally sensitized with ovalbumin (OVA), an increase in TLR3 mRNA levels was observed in lymphoid tissues that correlated with the inflammatory Th2 response, suggesting the importance of TLR3 in modulating asthma." (PMID 37426425, 2023).